LINC00355 (long independently transcribed non-coding RNA 355)
Gene: Long non-coding RNA gene on chromosome 13 (63,851,197 to 64,076,044, reverse strand). Ensembl gene ENSG00000227674.
Diseases named in the same sentence as LINC00355 in open-access papers:
LINC00355 is named in the same sentence as 23 diseases in open-access papers, as found by Europe PMC text mining. Sharing a sentence is not in itself a finding about the gene and the disease. The quoted sentences say what the papers report.
bladder cancer (6 papers, 2018 to 2024). "Another research unravels that LINC00355 expression is heightened in bladder cancer tissues and that highly-expressed LINC00355 contributes to poor prognosis in bladder cancer patients." (PMID 37827696, 2023). "Alternatively, exosome LINC00355 has been demonstrated to promote cisplatin resistance of bladder cancer cells via the miR-34b-5p/ABCB1 axis." (PMID 37784082, 2023). "Previous studies have shown that exosomal LINC00355 can facilitate the proliferation and invasion of bladder cancer cells as well." (PMID 37784082, 2023). "Previously, the frequent dysregulation of LINC00355 has been demonstrated in several cancers, such as bladder cancer, colorectal tumor, and lung cancer." (PMID 34603558, 2021). "LINC00355 is upregulated in bladder cancer samples and contributes to apoptosis inhibition, cell proliferation, and migration." (PMID 32517366, 2020). "A second example, found to be highly overexpressed is linc00355 (Δlog2 = 8.45, padj = 2.4 × 10−10), which has previously been observed to be overexpressed in bladder cancer." (PMID 29535801, 2018).
head and neck squamous cell carcinoma (4 papers, 2020 to 2022). A squamous cell carcinoma that arises from any of the following anatomic sites: lip and oral cavity, nasal cavity, paranasal sinuses, pharynx, larynx, and salivary glands. "Our findings firstly confirmed LINC00355 as a tumor promoter in glioma, which was in line with the tumor-promotive roles of LINC00355 in lung cancer and head and neck squamous cell carcinoma." (PMID 34603558, 2021). "In addition, LINC00355 and LINC00461 act as a miR-195 sponge to promote cell proliferation, invasion, and migration to up-regulate HOXA10 in head, neck squamous cell carcinoma, and lung adenocarcinoma, respectively." (PMID 35574307, 2022). "Similarly, LINC00355 has been shown to act as an miR-195 sponge, thereby upregulating HOXA10 and promoting migration, invasion, and EMT in head and neck squamous cell carcinoma." (PMID 34095215, 2021). "Moreover, previous studies showed that LINC00355 was highly expressed and enforced expression of LINC00355 promoted the development and progression of cancers in HCC, lung adenocarcinoma, and head and neck squamous cell carcinoma." (PMID 33381451, 2020).
colorectal cancer (2 papers, 2020 to 2021). A primary or metastatic malignant neoplasm that affects the colon or rectum. "Additionally, by binding to LINC00355 or GEFT 3’UTR, LIN28A moderated LINC00355-mediated GEFT expression, increased GEFT mRNA stability, and facilitated colorectal cancer formation, development, and aggression." (PMID 34868981, 2021).
lung adenocarcinoma (2 papers, 2020 to 2022). A carcinoma that arises from the lung and is characterized by the presence of malignant glandular epithelial cells. "LINC00355 knockdown suppressed cell proliferation, facilitated cell apoptosis in lung adenocarcinoma cells, and hampered tumor growth in lung adenocarcinoma xenografts by reducing microRNA-195 expression and increasing cyclin E1 expression." (PMID 33381451, 2020).
breast carcinoma (1 paper, 2022). "In order to gain a better understanding of the role LINC00355 plays in LSR breast cancer, we transiently silenced its expression with two siRNAs (siRNA1 and siRNA2, Supp." (PMID 35418131, 2022). "Taken together, LINC00355 induces cellular proliferation and invasion in both malignant breast cancer cell lines and long-term estrogen-deprived cell lines that mimic late-stage relapse." (PMID 35418131, 2022). "In summary, we show that LINC00355 previously found to have oncogenic potential is also highly expressed in breast cancer patient samples and cell lines." (PMID 35418131, 2022). "LINC00355 was only highly expressed in the late-stage relapse breast cancer patient samples (mean FPKM = 28.092)." (PMID 35418131, 2022). "Interestingly, we found that LINC00355 induced proliferation and cellular invasion in malignant breast cancer cell lines." (PMID 35418131, 2022). "LINC00355 is expressed greater than tenfold in breast cancer cell lines compared to the non-tumorigenic cell line MCF10-A." (PMID 35418131, 2022). "Overall, LINC00355 is more highly expressed in LSR compared to early-stage breast cancer patient samples, and in malignant compared to non-malignant cell lines and normal tissues." (PMID 35418131, 2022). "Taken together, we provide evidence that LINC00355 functions by binding to the MENIN protein, which decreases its occupancy at the promoter of CDKN1B, decreasing protein levels of p27Kip, increasing proliferation, and cellular invasion in late-stage relapse breast cancer models." (PMID 35418131, 2022).
colon adenocarcinoma (1 paper, 2019). "LINC00355 was positively correlated with distant metastasis, lymphatic metastasis and tumor stage, and negatively correlated with prognosis in colon adenocarcinoma." (PMID 30755833, 2019).
colon cancer (1 paper, 2020). "Survival analysis showed that higher expression of AC131571.1, ANO1‐AS2, ITCH‐IT1, ARHGEF26‐AS1, AP004609.1, LINC00491, KCNQ1OT1, MACROD2‐IT1, TSSC1‐IT1 or LINC00355 was correlated to poor OS in patients with colon cancer." (PMID 31965704, 2020).
diabetic nephropathy (1 paper, 2024). "In diabetic nephropathy LINC00355 has been shown to be upregulated and to increase endoplasmic reticulum stress thus contributing to podocyte injury." (PMID 38904047, 2024).
esophageal squamous cell carcinoma (1 paper, 2020). Esophageal squamous cell carcinoma (ESCC) is a type of esophageal carcinoma (EC) that can affect any part of the esophagus, but is usually located in the upper or middle third. "LINC00355, also named as lnc-PCDH9-13:1, has been found to abnormally expressed in multiple malignancies such as esophageal squamous cell carcinoma, papillary renal cell carcinoma, and hepatocellular carcinoma (HCC)." (PMID 33381451, 2020).
glioma (1 paper, 2021). A benign or malignant brain and spinal cord tumor that arises from glial cells (astrocytes, oligodendrocytes, ependymal cells). "Then, we performed loss-of-function and gain-of-function assays, confirming LINC00355 as a tumor promoter in glioma." (PMID 34603558, 2021). "The data revealed that repressing the expression of LINC00355 remarkably depressed the proliferative rates of glioma cells, while ectopic expression of LINC00355 led to notably increased growth curves." (PMID 34603558, 2021). "Our findings revealed the tumor-promotive roles of LINC00355 in the progression of glioma, indicating that LINC00355 exhibited ceRNA functions via modulating miR-1225/FNDC3B axis." (PMID 34603558, 2021). "LINC00355 expression was increased in glioma cell lines and specimens, and higher LINC00355 expression predicted advanced clinical progress and reduced overall survival and disease-free survival in glioma patients." (PMID 34603558, 2021). "Functionally, LINC00355 depletion promoted cell proliferation, invasion, and migration in glioma cells and induced apoptosis of glioma cells, whereas LINC00355 upregulation resulted in the opposite effects in vitro." (PMID 34603558, 2021). "In addition, in our gain-of-function assays, we observed that overexpression of LINC00355 displayed an opposite result compared to the downregulation of LINC00355 in glioma cells." (PMID 34603558, 2021). "Taken together, our results suggested that LINC00355 strongly promoted the development of glioma." (PMID 34603558, 2021). "Similar results from wound healing assays were also observed that LINC00355 overexpression could restore the suppressive impacts of si-FNDC3B#3 on glioma cell migration." (PMID 34603558, 2021). "Moreover, the caspase 3/9 activities were also evaluated and the data proved that enhancing expression of LINC00355 remarkably reduced the activities of caspase 3/9 in glioma cells, whereas depletion of LINC00355 significantly increased the caspase 3/9 activities." (PMID 34603558, 2021). "Besides, by analyzing five-year survival data, we confirmed that upregulation of LINC00355 was associated with shorter OS and DFS of glioma patients and could be an independent poor prognostic factor using multivariate Cox model." (PMID 34603558, 2021). "Firstly, qPCR was utilized for determining the levels of LINC00355 and FNDC3B in glioma cells after their miR-1225 was depleted or overexpressed." (PMID 34603558, 2021).
metastasis (1 paper, 2023). The spread or migration of cancer cells from one part of the body (where they first appeared) to another. "High expression of LINC00355 is correlated to big tumor size and more lymph node metastasis." (PMID 38125763, 2023).
prostate carcinoma (1 paper, 2019). A carcinoma that arises from epithelial cells of the prostate gland. "Upregulated LINC00355 was also associated with poor prognosis in prostate cancer." (PMID 30755833, 2019).
cancer (6 papers, 2020 to 2023). A tumor composed of atypical neoplastic, often pleomorphic cells that invade other tissues. "Upregulation of LINC00355 is associated with high cancer risk factors, including clinical features, and poor prognosis of patients." (PMID 38125763, 2023). "In summary, LINC00355 is a potential oncogene with great potential as a diagnostic marker and therapeutic target for cancer." (PMID 38125763, 2023). "Given that LINC00355 consistently exhibits high expression in various cancers and its related regulatory mechanisms have been linked with promoting cancer, future research is required to better understand the molecular mechanisms of LINC00355." (PMID 38125763, 2023). "Upregulation of LINC00355 has been identified as a high‐risk factor in cancer patients and its increased expression is associated with poorer overall survival, recurrence‐free survival, and disease‐free survival." (PMID 38125763, 2023). "LINC00355 has been reported aberrantly over-expressed and associated with poor prognosis in various types of cancer." (PMID 33111744, 2020). "High LINC00355 expression is associated with poor prognosis (overall survival, recurrence‐free survival, and disease‐free survival) and advanced pathological features in various cancers." (PMID 38125763, 2023). "LINC00355 was shown to promote cancer cell proliferation and tumor growth in xenograft animals by regulating the transcription of three genes (ITGA2, RAD18, and UBE3C) and participating in seven ceRNA axes." (PMID 38125763, 2023). "At the posttranscriptional level, LINC00355 acts as a ceRNA to regulate eight downstream miRNA/mRNA axes to promote cancer progression." (PMID 38125763, 2023). "LINC00355 plays a role in regulating biological behaviors such as proliferation, invasion, migration, and apoptosis of cancer cells." (PMID 38125763, 2023). "LINC00355 was shown to promote invasion and migration in cancer cells and xenograft animals by regulating the transcription of three downstream genes (ITGA2, RAD18, and UBE3C) and participating in six ceRNA axes." (PMID 38125763, 2023). "LINC00355 has the potential to serve as a new biomarker and therapeutic target for cancer treatment." (PMID 38125763, 2023). "Our analysis revealed that LINC00355 was markedly overexpressed in six types of cancer (ALL, AML, ESCA, LUAD, LUSC, and SKCM) in the TCGA database." (PMID 38125763, 2023). "Studies have shown that some other LINC00355 downstream targets promote chemotherapy resistance in cancer." (PMID 38125763, 2023). "LINC00355 promotes the malignant phenotype of cancer cells through its function in eight ceRNA regulatory axes." (PMID 38125763, 2023). "LINC00355 expression was found to be upregulated in cell lines of eight different types of cancer compared with control cell lines." (PMID 38125763, 2023). "LINC00355 is located on chromosome 13q21.31 and has been consistently found to be highly expressed in various cancers, making it a promising biomarker in cancer diagnosis." (PMID 38125763, 2023). "To further investigate the differences in LINC00355 expression across various cancers, we conducted a pan‐cancer analysis using The Cancer Genome Atlas (TCGA) database and compared our findings with existing studies." (PMID 38125763, 2023). "Its expression is markedly upregulated in at least eight types of cancer, and thus LINC00355 has great potential as a cancer biomarker." (PMID 38125763, 2023). "High expression of LINC00355 predicts poor prognosis in five cancers (BCa, CRC, GBM/LGG, GC, and LUSC)." (PMID 38125763, 2023).
cancer (continued). "LINC00355 was also found to be markedly upregulated in seven types of cancer tissues compared with normal tissues, namely GBM/LGG, LUAD, LUSC, HCC, GC, CRC, and BCa." (PMID 38125763, 2023). "LINC00355 induces chemotherapy resistance in cancer cells by regulating five downstream genes, namely HMGA2, ABCB1, ITGA2, WNT10B, and CCNE1 genes." (PMID 38125763, 2023). "LINC00355 promotes the invasion and migration process of cancer cell lines through five ceRNA axes." (PMID 38125763, 2023). "LINC00355 plays a role in regulating two signaling pathways that promote cancer progression." (PMID 38125763, 2023). "LINC00355 plays a role in regulating various biological processes such as cell cycle progression, proliferation, apoptosis, epithelial‐mesenchymal transition, invasion, and metastasis of cancer cells." (PMID 38125763, 2023). "In CRC, LINC00355 promotes ITGA2 expression by recruiting GTF2B, a critical transcription factor involved in regulating various cancers, thereby promoting cancer progression." (PMID 38125763, 2023). "LINC00355 also inhibits the Wnt/β‐catenin signaling pathway in HCC by sponging miR‐217‐5p, thus promoting cancer progression." (PMID 38125763, 2023).
tumor (6 papers, 2019 to 2024). "In CRC, high expression of LINC00355 is associated with larger tumor size and more lymph node metastases." (PMID 38125763, 2023). "Recent studies have shown that LINC00355 plays an important role in tumorigenesis and tumor progression." (PMID 38125763, 2023). "LINC00355 promoted tumor metastasis in vivo in a xenograft mouse model through the LINC00355/miR‐424‐5p/HMGA2 axis in BCa." (PMID 38125763, 2023). "LINC00355 is a newly discovered long noncoding RNA that promotes tumor growth." (PMID 38125763, 2023). "Differential expression of LINC00355 in tumor cells, tissues, and exosomes." (PMID 38125763, 2023). "However, the function of LINC00355 in tumor progression was rarely reported." (PMID 34603558, 2021). "CTD-2066L21.3, LINC00355, CTD-2555C10.3, OGFRP1, and LINC00862 were found to be substantially expressed in tumor cells but expressed at low levels in normal cells." (PMID 38710798, 2024). "Mechanistic studies identified a novel regulatory mechanism of LINC00355/miR-1225/FNDC3B axis in carcinogenesis and metastasis, suggesting a novel clue for tumor treatments." (PMID 34603558, 2021). "Consistent with the previous report, we also demonstrated that LINC00355 expression was remarkably up-regulated in CRC tumor tissues versus normal tissues and CRC patients with high LINC00355 expression had a poor overall survival." (PMID 33381451, 2020). "The expression of LINC00355 in 30 pairs of lung SCC specimens (Tumor) and the corresponding adjacent non-tumor (Normal) tissues were determined using qRT-PCR." (PMID 33111744, 2020).
LINC00355 also shares sentences with these, for which no sentence is quoted: colorectal tumor (1 paper); hepatocellular carcinoma (1); lung carcinoma (1); lung squamous cell carcinoma (1); lymph node metastasis (1); papillary renal cell carcinoma (1); renal fibrosis (1); schizophrenia (1); Sepsis (1).